PNP (purine nucleoside phosphorylase)
Description:
Catalyzes the phosphorolytic breakdown of the N-glycosidic bond in the beta-(deoxy)ribonucleoside molecules, with the formation of the corresponding free purine bases and pentose-1-phosphate. Preferentially acts on 6-oxopurine nucleosides including inosine and guanosine.
Synonyms: NP; PUNP; PRO1837
Tractability: Small molecule: a drug acting on it is in phase 2 or 3 trials; a structure with a bound ligand is known; a high-quality ligand is known; it has a high-quality binding pocket; it belongs to a druggable protein family. Antibody: its Gene Ontology location is reachable by antibodies, with high confidence. PROTAC: ubiquitination databases record sites on it; its protein half-life has been measured; a small molecule that binds it is known.
Target class: Enzyme; Transferase
Gene: Protein-coding gene on chromosome 14 (20,461,992 to 20,477,094, forward strand). Ensembl gene ENSG00000198805.
Subcellular location: Cytoplasm, cytosol
Subcellular location (Human Protein Atlas): Cytosol
Pathways (Reactome):
Metabolism: Purine catabolism; Purine salvage
Disease: Defective PNP disrupts phosphorolysis of (deoxy)guanosine and (deoxy)inosine
Drug ADME: Ribavirin ADME
Immune System: Neutrophil degranulation
Gene Ontology:
Molecular function: guanosine phosphorylase activity; identical protein binding; nucleoside binding; phosphate ion binding; protein binding; purine nucleobase binding; purine-nucleoside phosphorylase activity; catalytic activity; pentosyltransferase activity
Biological process: allantoin metabolic process; dAMP catabolic process; deoxyadenosine catabolic process; deoxyinosine catabolic process; immune response; IMP catabolic process; inosine catabolic process; nicotinamide riboside catabolic process; nucleobase-containing compound metabolic process; nucleotide biosynthetic process; positive regulation of alpha-beta T cell differentiation; positive regulation of interleukin-2 production; positive regulation of T cell proliferation; purine-containing compound salvage; response to xenobiotic stimulus; urate biosynthetic process; deoxyguanosine catabolic process; guanosine catabolic process; NAD+ biosynthetic process via the salvage pathway; nucleoside metabolic process
Cellular component: cytoplasm; cytosol; extracellular exosome; extracellular region; ficolin-1-rich granule lumen; secretory granule lumen
Genetic constraint (gnomAD): Loss-of-function variants: 18 observed, 26.82 expected, observed/expected ratio (o/e) 0.67, 90% interval 0.46 to 1. The upper end of that interval is the gene's LOEUF score, 1, which puts it in group 4 of 6, group 1 being the genes least tolerant of losing a copy. Missense variants: 320 observed, 379.74 expected, observed/expected ratio (o/e) 0.84, 90% interval 0.77 to 0.92. Synonymous variants: 116 observed, 131.87 expected, observed/expected ratio (o/e) 0.88, 90% interval 0.76 to 1.03.
Gene-disease validity (ClinGen):
ClinGen rates the evidence that PNP causes each of these diseases.
purine nucleoside phosphorylase deficiency (autosomal recessive): Definitive. Purine nucleoside phosphorylase (PNP) deficiency is a disorder of purine metabolism characterized by progressive immunodeficiency leading to recurrent and opportunistic infections, autoimmunity and malignancy as well as neurologic manifestations.
Homologues: Orthologues: chimpanzee PNP (99% identical), macaque PNP (96% identical), rabbit PNP (90% identical), pig PNP (88% identical), guinea pig PNP (86% identical), mouse Pnp (84% identical), dog PNP (83% identical), mouse Pnp2 (83% identical), rat Pnp (67% identical), tropical clawed frog pnp (65% identical), zebrafish pnp5a (63% identical), zebrafish pnp5b (57% identical), and 3 more. Paralogues in human: MTAP (25% identical).
Diseases named in the same sentence as PNP in open-access papers:
PNP is named in the same sentence as 116 diseases in open-access papers, as found by Europe PMC text mining. Sharing a sentence is not in itself a finding about the gene and the disease. The quoted sentences say what the papers report.
Immunodeficiency (26 papers, 2009 to 2025). Failure of the immune system to protect the body adequately from infection, due to the absence or insufficiency of some component process or substance. "Complete deficiency of PNP (a very rare, inherited disorder) leads to severe combined immunodeficiency, lymphopenia, autoimmune hemolytic anaemia and thrombocytopenia in humans." (PMID 41469749, 2025). "Amid the conflict, a Ukrainian newborn screened positive for an extremely rare severe combined immunodeficiency (SCID)–purine nucleoside phosphorylase (PNP) deficiency." (PMID 40981309, 2025). "Across patients with PNP deficiency, recurring PNP mutations have been identified that lead to immune dysfunction and susceptibility to infections." (PMID 40519286, 2025). "Deficiency of purine nucleoside phosphorylase (PNP) has been linked to immunodeficiency and autoimmune disorders." (PMID 39191722, 2024). "More than 35 PNP gene mutations have been identified in individuals with a purine nucleoside phosphorylase deficiency, an immune system disorder in which the body cannot fight foreign invaders such as bacteria and viruses." (PMID 36672262, 2023). "Purine nucleoside phosphorylase deficiency and adenosine deaminase deficiency exhibit aberrant accumulation of dGTP and dATP, respectively and lead to severe immunodeficiencies with insufficient T- and B-cell proliferation." (PMID 35927450, 2022). "Purine nucleoside phosphorylase (PNP) deficiency is a rare inherited disorder, resulting in severe combined immunodeficiency." (PMID 34698070, 2021). "Lastly, the pattern of abundance changes that we observed specifically in lymph nodes for purine nucleoside phosphorylase, which mimicked our previous finding in the liver of the same rats, tends to confirm its value as an immune deficiency biomarker." (PMID 34445271, 2021). "Classic genetic studies have shown how mutations in human purine nucleoside phosphorylase cause immunodeficiency due to T-cell dysfunction." (PMID 33878133, 2021). "While mutations in human PNP cause severe combined immunodeficiency, this phenotype appears to be due to apoptosis of T cells." (PMID 33878133, 2021). "A loss of PNP activity or accumulation of one or more enzyme substrates has been linked extensively to immune deficiency." (PMID 31600945, 2019). "Purine nucleoside phosphorylase (PNP) deficiency is a rare autosomal recessive metabolic disorder that results in combined immunodeficiency, neurologic dysfunction and autoimmunity." (PMID 19584574, 2009). "In another report, ATOs were used to evaluate the effects of purine nucleoside phosphorylase (PNP) inactivation, an enzyme mediating the breakdown and recycling of guanine nucleoside, whose deficiency in humans is associated with both immunodeficiency and autoimmunity." (PMID 39167072, 2024). "PNP deficiency results in marked T lineage lymphopenia and severe immunodeficiency." (PMID 35641516, 2022). "PNP inactivation is paradoxically associated with both immunodeficiency and autoimmunity, but the mechanistic basis for these manifestations is undefined and whether they can be functionally uncoupled remains unknown." (PMID 35653193, 2022). "Interestingly, mutations in human PNP lead to severe combined immunodeficiency disease due to T-cell dysfunction." (PMID 33878133, 2021). "In spite of the theoretical concern regarding the association of PNP inhibition and immunodeficiency, we showed that in normal healthy mice, IH stimulates the proliferation of CD4+ and CD8+-T and CD19+-B cells after direct contact or systemic previous treatment." (PMID 26701750, 2015). "This work reveals that one purine metabolism gene protects against immunodeficiency and autoimmunity via independent mechanisms operating in distinct immune lineages and identifies PNP as a potentially novel metabolic immune checkpoint." (PMID 35653193, 2022).
Immunodeficiency (continued). "Additional genetic defects in MTHFD1, RMRP, CORO1A, PNP, DOCK8, ATM, and BCL11B, among others also cause combined immunodeficiencies, which can be detected by low TREC copy number analysis." (PMID 29713328, 2018). "Purine nucleoside phosphorylase (PNP) deficiency, a rare autosomal recessive metabolic disease causes combined immunodeficiency and developmental delay, hypotonia, and spasticity." (PMID 28674683, 2017). "Genetic deficiency of Ado deaminase (ADA1) or purine nucleoside phosphorylase (PNP) disrupts intracellular purine metabolism and leads to severe-combined immunodeficiency (SCID) with insufficiency of functional lymphocytes." (PMID 27066009, 2016). "Among CID participants, one had severe combined immunodeficiency (SCID) status post-hematopoietic stem cell transplant, three had CID with syndromic features, two had purine nucleoside phosphorylase (PNP) deficiency, three had 22q11 deletion syndrome, and 25 had other types of CID." (PMID 39906736, 2024). "Collectively, our findings demonstrate that PNP protects against both immunodeficiency and autoimmunity via hitherto unknown and independent mechanisms operating in distinct immune lineages." (PMID 35653193, 2022). "Evidence for the immune-regulatory roles of nucleosides was provided by the identification of immune dysfunction in patients with hereditary loss-of-function mutations in two genes responsible for the breakdown of purine nucleosides: ADA and purine nucleoside phosphorylase (PNP)." (PMID 40519286, 2025). "While neither HA19 nor HA21 show evidence of immune dysfunction characteristic of PNP deficiency, the degree of reduction of PNP expression in these patients is dramatic, and may be related to the etiology of their hemolytic anemia." (PMID 22509282, 2012).
autoimmune disease (9 papers, 2015 to 2025). A disorder resulting from loss of function or tissue destruction of an organ or multiple organs, arising from humoral or cellular immune responses of the individual to their own tissue constituents. "Recent studies have shown that purine nucleoside phosphorylase (PNP) deficiency is associated with an increased risk of developing autoimmune disorders, such as lupus and autoimmune hemolytic anemia." (PMID 37103652, 2023). "PNP was involved in lymphocyte purine metabolism, and mutations in this gene was related to a deficiency in the immunity of lymphocytes T and B, being linked to some autoimmune diseases, including systemic lupus erythematosus." (PMID 41241706, 2025). "Abnormal expression of PNP will lead to blockage of the degradation of purine nucleosides inosine and guanosine, causing accumulation of metabolites in mitochondria, blockage of DNA synthesis and abnormal cell function, and participate in the occurrence of inflammation and autoimmune diseases." (PMID 38026929, 2023). "However, although the three HC-enriched MEs were not correlated with the gut microbiota or with inflammation indicators, these peptides are also of interest: VVTNAAGGLNPKFEVGDIML from PNP binds to HLA-B7, while loss of PNP function can lead to severe T cell immunodeficiency or autoimmune disease." (PMID 34276644, 2021). "Such PNP inhibitors have been investigated as potential treatments for the uncontrolled T and B cell proliferation seen in leukemia, autoimmune diseases, transplant rejection, and graft vs. host disease." (PMID 32695102, 2020). "These patients present with lymphopenia and all along it was thought that inhibition of PNP would lead to immune-suppression and hence PNP inhibitors were developed for autoimmune diseases and hematologic malignancies." (PMID 30518409, 2018).
prostate carcinoma (9 papers, 2012 to 2025). A carcinoma that arises from epithelial cells of the prostate gland. "Knockdown of the PNP gene inhibited migration and invasion of prostate cancer and bladder cancer cell lines." (PMID 41502507, 2025). "In prostate cancer, miR-1 inhibited cell proliferation, migration and invasion by suppressing the expression of purine nucleoside phosphorylase (PNP)." (PMID 25196260, 2014). "miR-1 was found to target the oncogene purine nucleoside phosphorylase (PNP) in prostate cancer, thus suppressing cell migration and invasion, in agreement with the effects of PNP silencing in prostate cancer lines PC3 and DU145." (PMID 23325049, 2013). "Additionally, decreasing miR-1/miR-133a cluster expression promotes oncogenesis by increasing PNP expression in prostate cancer." (PMID 26472186, 2015). "The inferred subset GRN from the PC3 prostate cancer cell line suggests several genes as suppressors of SDHB, such as PNKB, PWP1, PNP, HADH, HTATSF1, and BAZ1B, among which PWP1, HTATSF1, and BAZ1B are transcription regulators." (PMID 33168813, 2020). "Moreover, miR-1 represses genes such as PNP (purine nucleoside phosphorylase) and PTMA (prothymosin-α), leading to down-regulation of pathways regulating the cell cycle, mitosis, DNA replication, and actin dynamics in prostate cancer." (PMID 28537886, 2017).
Autoimmunity (6 papers, 2009 to 2024). The occurrence of an immune reaction against the organism's own cells or tissues. "To determine if PNP inactivation in mice engenders similar autoimmunity-associated phenotypes we used MRL-LPR mice, which are prone to the development of systemic autoimmunity and B cell–dependent nephritis." (PMID 35653193, 2022). "The authors used synthetic inhibitors of PNP to clarify the pathway through which PNP deficiency is toxic to developing T cells and also propose a mechanism for the association of PNP deficiency with autoimmunity through effects on TLR7." (PMID 35968787, 2022). "In MRL-LPR mice, which are prone to developing autoimmunity, acceleration of lymphoproliferative and lupus-like autoimmunity was observed with five weeks of exposure to a PNP inhibitor." (PMID 35968787, 2022).
leukemia (6 papers, 2015 to 2025). A malignant (clonal) hematologic disorder, involving hematopoietic stem cells and characterized by the presence of primitive or atypical myeloid or lymphoid cells in the bone marrow and the blood. "PNP inhibitors have been developed for the treatment of leukemia wherein they caused cell death via up-regulation of the apoptotic caspase-8, -9, and -3 and dGTP accumulation." (PMID 33935764, 2021). "Recently, phase I and II clinical trials have been conducted to evaluate the efficacy of these PNP inhibitors in treating patients with leukemia." (PMID 41502507, 2025). "IH (Forodesine) and DADMe-ImmH (Ulodesine) are potent inhibitors of human PNP that have been used in human clinical trials against leukemia and gout." (PMID 25909893, 2015). "The PNP inhibitor, forodesine, has shown therapeutic effects in the treatment of leukemias." (PMID 33935764, 2021). "IH (forodesine) is also effective as a PNP inhibitor against leukemia cells." (PMID 26701750, 2015).
T-cell immunodeficiency (6 papers, 2016 to 2025). A broad classification of disorders that affect the cell-mediated aspect of the immune response. "The most profound phenotype observed in PNP-deficient patients, a near complete T cell immunodeficiency, is linked to the uncontrolled expansion of purine nucleotide pools in developing thymocytes following PNP inactivation." (PMID 40519286, 2025). "PNP-KO mice manifest minor alterations in T cell development and fail to recapitulate the severe T cell immunodeficiency observed in humans with inactivating mutations in PNP." (PMID 35653193, 2022). "PNP is expressed across immune lineages, but PNP deficiency is associated with T cell immunodeficiency." (PMID 35653193, 2022). "PNP-deficient patients show not only T cell immunodeficiency but also various autoimmune phenotypes, including systemic lupus erythematosus, autoimmune hemolytic anemia, and systemic juvenile idiopathic arthritis with macrophage activation syndrome." (PMID 35653193, 2022). "The synthetic lethal interaction between PNP and SAMHD1 inactivation explains one of the enduring mysteries regarding the mechanisms responsible for T cell immunodeficiency in patients with PNP-inactivating mutations." (PMID 35653193, 2022). "In addition to T cell immunodeficiency, loss of PNP function associates with various autoimmune and inflammatory phenotypes in humans." (PMID 35653193, 2022). "Autosomal recessive defects in PNP enzymes were recognized in the 1970's among patients with a profound T cell immunodeficiency." (PMID 32695102, 2020). "In the mid-1970s it was reported that a child lacking purine nucleoside phosphorylase (PNP) activity in their red blood cells had severe T-cell immunodeficiency whilst retaining normal B-cell immunity." (PMID 39962329, 2025). "We also explain why genetic or pharmacologic PNP inactivation in mice does not recapitulate the severe T cell immunodeficiency observed in humans." (PMID 35653193, 2022).
chronic lymphocytic leukemia (5 papers, 2010 to 2025). "Forodesine (BCX-1777) is a potent inhibitor of human PNP and which induces apoptosis of chronic lymphocytic leukaemia (CLL) cells." (PMID 22068816, 2012). "Recently forodesine, a purine nucleoside phosphorylase inhibitor, was found to induce apoptosis in leukemic cells of chronic lymphocytic leukemia patients by increasing the dGTP levels." (PMID 20981156, 2010). "PNP is considered as a therapeutic target in malignant lymphoproliferative diseases as treatment with its inhibitor Forodesine (BCX-1777) induced apoptosis of chronic lymphocytic leukemia (CLL) cells." (PMID 31581454, 2019). "PNP inhibitors, including forodesine (BCX-1777), effectively inhibit cell growth by triggering apoptosis in patients with chronic lymphocytic leukemia." (PMID 41502507, 2025).
gout (5 papers, 2015 to 2025). A condition characterized by painful swelling of the joints, which is caused by deposition of urate crystals. "Uric acid, which causes gout, is the end product of purine catabolism, synthesized by xanthine oxidase, guanine deaminase, adenine deaminase, purine nucleoside phosphorylase, and 5-nucleotidase II." (PMID 36013310, 2022).
breast carcinoma (4 papers, 2023 to 2024). "Accordingly, our results implicated that PNP, as well as PPP/NPP cells, are subsets of MKI67+ proliferative cells crucial for oestrogen‐dependent breast cancer growth, which correlated with the results from our ST analyses." (PMID 38282415, 2024). "Furthermore, purine nucleoside phosphorylase (PNP) fusion protein with ANV enhanced cytotoxicity against breast cancer." (PMID 37446286, 2023).
combined immunodeficiency (4 papers, 2019 to 2024). A broad classification of inherited disorders presenting at birth that affect both the cell-mediated and humoral aspects of the immune response. "ADA and PNP deficiency causes severe combined immunodeficiency (SCID) with loss of T and B lymphocytes." (PMID 34986329, 2022).
hyperuricemia (4 papers, 2016 to 2025). An abnormally high level of uric acid. "Further research confirmed that CCE has the potential to regulate the mRNA expression of ADA, PNP, and JUN in the kidney, thereby alleviating hyperuricemia associated with anti-inflammatory activity." (PMID 38026974, 2023). "We conclude that CCE has anti-hyperuricemia effects and alleviates renal inflammation in a rat model of hyperuricemia, and these efficacies are associated with the reversal of increased ADA, PNP, and JUN mRNA expression in renal tissues." (PMID 38026974, 2023). "Using hyperuricemia mice induced by high-nucleoside diet, we have identified the role of L. plantarum in inhibiting the activity of hepatic XOD and PNP for urate synthesis." (PMID 37468996, 2023).
lymphopenia (3 papers, 2018 to 2025). Reduction in the number of lymphocytes. "Lymphopenia noted in PNP deficient patients is primarily related to constitutive activation leading to immune exhaustion." (PMID 30518409, 2018).